MIR514A2 (microRNA 514a-2)
Synonyms: hsa-mir-514-2; MIR514-2; MIRN514-2; hsa-mir-514a-2
Gene: MicroRNA gene on chromosome X (147,281,943 to 147,282,030, reverse strand). Ensembl gene ENSG00000207866.
Homologues: Orthologues: chimpanzee ptr-mir-514-2 (100% identical), chimpanzee ptr-mir-514-2 (99% identical), chimpanzee MIR514-1 (98% identical), macaque mml-mir-514a (98% identical), dog MIR514 (75% identical), mouse Mir509 (68% identical), rabbit ocu-mir-506 (41% identical). Paralogues in human: MIR514A3 (100% identical), MIR514A1 (99% identical), MIR509-1 (82% identical), MIR514B (73% identical), MIR509-3 (68% identical), MIR506 (59% identical), MIR507 (59% identical), MIR513A2 (57% identical), MIR513B (56% identical).